Y_RNA (Y RNA )
Gene: Miscellaneous RNA gene on chromosome 3 (5,086,178 to 5,086,279, reverse strand). Ensembl gene ENSG00000207283.
Homologues: Orthologues: chimpanzee Y_RNA (98% identical), macaque Y_RNA (94% identical). Paralogues in human: Y_RNA (90% identical), RNY3 (89% identical), Y_RNA (89% identical), Y_RNA (88% identical), Y_RNA (87% identical), RNY3P1 (86% identical), Y_RNA (86% identical), RNY3P14 (85% identical), Y_RNA (85% identical), Y_RNA (84% identical), RNY3P10 (83% identical), RNY3P4 (83% identical), and 96 more.